BRAF (B-Raf proto-oncogene, serine/threonine kinase)
Diseases named in the same sentence as BRAF in open-access papers (continued):
Sharing a sentence is not in itself a finding about the gene and the disease.
melanoma (continued). "In the CaCTUS study, patients with BRAF mutant melanoma on the intervention arm switch from targeted treatment to immunotherapy when there is evidence of molecular response, as defined by a decrease in mutant BRAF VAF of ≥80% by ddPCR." (PMID 38201222, 2023). "Importantly, the experimental upregulation of miR-7 and miR-126 3p restored responses to BRAF inhibitors in melanoma cell lines." (PMID 37958863, 2023). "Another sample showed coexisting NRAS and NF1 mutations, supporting the three-group melanoma classification (BRAF-mutant, RAS-mutant, non-BRAF-mutant/non-NRAS-mutant)." (PMID 36901733, 2023). "Besides its ability to evade drug toxicity, melanoma can also develop adaptive tumor cell plasticity via tumor-microenvironment-dependent modifications, in response to treatment with BRAF/MEK inhibitors." (PMID 37370757, 2023). "Despite the clear benefits of targeted therapies for BRAF-mutated melanoma in other regions, there is no clear path to prepare LA for a sustainable personalized medicine approach to this disease." (PMID 36998456, 2023). "It has been suggested that the combined inhibition of AURKA and FOXM1 could be considered a good strategy for patients with melanoma who are refractory to the combined use of BRAF/MEK inhibitors." (PMID 37259298, 2023). "However, the number of studies focusing on the identification of lncRNAs as predictors of response to targeted therapy in BRAF-mutant melanoma patients is limited." (PMID 37627054, 2023). "Similarly, BRAF inhibitor monotherapy is also ineffective in BRAF-mutated CRC, although BRAF inhibitors have shown striking efficacy in BRAF-mutant melanoma." (PMID 36849918, 2023). "Case 1: A 37-year-old man seen by Dermatology for a superficial spreading, BRAF-positive malignant melanoma on his right flank diagnosed in May 2019." (PMID 36604647, 2023). "Patient 1 was a 51-year-old woman immunosuppressed with azathioprine for systemic lupus erythematosus, presented with cutaneous stage-IV BRAF-wildtype melanoma in May 2017." (PMID 35841421, 2023). "The molecular subtypes with the highest BM incidence are epithelial growth factor receptor-mutated non-small cell lung cancer (NSCLC), BRCA1, triple-negative (TN), and HER2+ breast cancers, and BRAF-mutated melanoma." (PMID 37484759, 2023). "Next, the 27 migration-enhancing compounds were validated at four concentrations, 1, 5, 25, and 125 μM, in four human melanoma cell lines, SK-MEL-30 and IPC-298 which harbor NRAS mutations, and SK-MEL-3 and A-375 which harbor BRAF mutations, using the IncuCyte system." (PMID 36774779, 2023). "Subpopulation of melanoma slow cycling cells was not related to BRAF, NRAS, and PTEN mutation status but was characterized by increased invasive potential." (PMID 36533319, 2023). "Here, we show that prolonged exposure of BRAF-mutant melanoma cells to vemurafenib treatment leads to the emergence of drug-resistant melanoma subpopulations characterized by an increase in CD271 expression with induced Akt3 and Nox4 activity and the subsequent EMT process." (PMID 37189846, 2023). "In our study, we evaluated the prognostic value of MMP2 expression in melanoma, the OS of patients with high MMP2 expression was significantly lower than patients with low MMP2 expression, and this trend was more pronounced in patients with BRAF mutation." (PMID 36788565, 2023). "For example, the efficacy of vemurafenib in targeting BRAF V600E mutation in patients with melanoma, was not reproducible in colon cancers." (PMID 36639625, 2023). "In accordance with the published data, the three ALM melanomas in our cohort were not BRAF mutated; rather, they carried NRAS, KIT and NF1 mutations." (PMID 36765773, 2023).
melanoma (continued). "However, a retrospective study performed on melanoma patients with LMD between 2011 to 2019 reported a median OS of 2.9 months among patients treated with either BRAF/MEK inhibitors or anti-PD1." (PMID 36980770, 2023). "Notably, in colorectal cancer, BRAF inhibitors show limited efficacy, potentially due to the feedback activation of EGFR, whereas ectopic expression of EGFR in melanoma cells has been shown to elicit resistance to BRAF inhibitors." (PMID 36219477, 2023). "Most melanoma patients have non-overlapping “driver” mutations in either BRAF, NRAS, or NF1 genes based on Next-Gen sequencing." (PMID 37444637, 2023). "In BRAF mutant melanomas, the combination of targeted and immunotherapy has been tested in preclinical models, and clinical trials are currently underway, suggesting that a combination of BRAFi, MEK inhibitor, and PD‐1 blockade may be feasible." (PMID 37183363, 2023). "Vemurafenib is a BRAF inhibitor that has significantly changed the therapeutic landscape in melanoma, prolonging the survival of patients with unresectable metastatic or BRAFV600E-mutated melanomas." (PMID 36827549, 2023). "Similarly, in-frame deletion mutations involving exons 2-8, which includes the Ras-binding domain, were also detected in D/T combination-resistant BRAF melanomas in patients, albeit at a low frequency of 0.4%." (PMID 37834284, 2023). "Additionally, SEMA6A plays a pivotal role in orchestrating the coordinated escape of melanoma cells from concurrent BRAF/MEK inhibition, signifying its potential as a dependable marker for immediate therapeutic benefits of such inhibition." (PMID 38036577, 2023). "Recent achievements in research into biological mechanisms in melanoma have led to new potential treatment strategies, e.g., immune therapies and targeting BRAF-related signal transduction pathways, and new understanding of regulatory proteins involved in DNA damage repair." (PMID 36229655, 2023). "Indeed, a combination of D/T with the PD-1 antibody pembrolizumab prolonged antitumor responses and progression-free survival of BRAF-mutant melanoma patients." (PMID 37834284, 2023). "Moreover, USP5 deprivation reversed resistance to vemurafenib and sensitized BRAF-mutant melanoma cells to apoptosis initiated by BRAF inhibitors." (PMID 36694209, 2023). "Through leveraging gene signatures in predicting the durability of drug response, this study also identified the expression levels of the genes MMP2, SPARC, and HMOX1 as having a good predictive value in predicting the emergence of chemoresistance to BRAF/MEK inhibitor therapy in melanomas." (PMID 37176114, 2023). "This study states that BRAF/NRAS mutations within a nevus do not play a major role in the development of melanoma from nevi." (PMID 36676131, 2023). "A phase I/II clinical trial, KEYNOTE-022, demonstrated that in melanoma patients with poor prognostic factors, the mPFS was 16.0 months in the BRAF-MEK inhibitor (dabrafenib and trametinib) and pembrolizumab group versus 10.3 months in dabrafenib and trametinib group." (PMID 37345194, 2023). "We investigated whether cannabinoids would alter the sensitivity of melanoma to BRAF inhibitor therapy." (PMID 37237519, 2023). "Several factors produced by melanoma cells have been reported to promote the inflammation process, and inflammatory niches have been reported to adapt to and confer drug tolerance to BRAF and MEK inhibitors early during treatment." (PMID 37174072, 2023). "PLX4032 prolongs survival in patients with BRAF-mutant melanoma." (PMID 36834830, 2023). "This molecular analysis of patients with resected melanoma brain metastases found that BRAF V600E alteration is an important translational biomarker associated with worse clinical outcomes, differential microenvironmental composition, and benefit from immunotherapy." (PMID 37589977, 2023).
melanoma (continued). "One of the studies showed a reduction in pyruvate-to-lactate conversion in the BRAF mutant melanoma cell line compared to the vehicle control, whereas an increased pyruvate-to-lactate conversion was recorded in the BRAF wildtype melanoma cell line compared to vehicle control." (PMID 37233647, 2023). "Melanoma cell responsiveness to BRAF kinase inhibitors (BRAFi) may vary depending on the level of expression of the BRAF gene/BRAF mRNA level, and approximately 15% of melanomas are characterized by intrinsic resistance mechanisms." (PMID 36765875, 2023). "BRAF mutations are often found in common or atypical nevi but are not enough to cause the occurrence of melanoma." (PMID 36676131, 2023). "Here we report the case of a patient with TWT melanoma with a bona fide MAP2K1 mutation without any BRAF mutations." (PMID 36901951, 2023). "BRAF inhibitors, including vemurafenib and dabrafenib, have demonstrated efficacy in patients with BRAF-mutated melanoma; however, no targeted therapy has been approved for patients with melanoma harboring NRAS mutations to date." (PMID 36600247, 2023). "The treatment of BRAFV600E mutant melanoma has been revolutionized by BRAF inhibitors." (PMID 36967525, 2023). "Based on another series from our group, fRNB may also be more frequent after treatment with BRAF-/MEK inhibitors in patients treated for BRAF V600-mutant melanoma brain metastases with SRS/SRT." (PMID 37174026, 2023). "Furthermore, BRAFi inhibited ERK1/2 activity and lowered RIPK4 protein levels in BRAF-mutated melanoma cells (A375 and WM266.4), while in wild-type BRAF cells (BLM and LoVo), both inhibitors decreased the level of RIPK4 and enhanced ERK1/2 activity." (PMID 36765875, 2023). "However, a meta-analysis conducted in 2017 showed an overall discrepancy rate of 13.4% of the BRAF status between the primary melanoma and the matched metastasis." (PMID 38003476, 2023). "Has the question of sequencing for patients with BRAF+ melanoma been put to rest?" (PMID 37507765, 2023). "Similarly, combining immunotherapy with targeted therapy agents, such as BRAF inhibitors, has shown improved outcomes in patients with BRAF-mutant melanoma." (PMID 37111629, 2023). "NSCLC, breast cancer and melanoma, which are primary tumor types of LMC may have marker mutations such as EGFR, HER2 and BRAF respectively." (PMID 37096065, 2023). "Furthermore, a matching-adjusted study found that ICI treatment improved overall survival (OS) of BRAF-mutant melanoma patients when compared to MAPKi." (PMID 37435085, 2023). "Interestingly, in melanoma and thyroid papillary carcinoma, TERT mutation is widely found to be associated with BRAF p.V600E mutations." (PMID 36831610, 2023). "Therefore, we conducted this retrospective study to compare the efficacy of different adjuvant treatment for Stage III BRAF V600 mutant melanoma in our single centers." (PMID 37016119, 2023). "Notably she had stage IV melanoma (BRAF wildtype) with sites of disease including her right thigh, lung and lymph nodes." (PMID 36895912, 2023). "Similarly, treating WM164 with a BRAF inhibitor in the presence of recombinant TGFβ1 (200 pg/mL) improved colony formation of the melanoma cells, despite the BRAF inhibitor, indicating the role of TGFβ1 in drug resistance." (PMID 36980770, 2023). "Regarding environmental and genetic factors, NAMs are more likely than de novo melanomas to be located on non-chronically sun-damaged skin, such as on the trunk and extremities, which in turn is more frequently associated with BRAF mutations." (PMID 36765817, 2023). "From the melanoma cell lines A375 and SkMel28, both mutated on BRAF, resistant cell lines called A375RES and SkMel28RES were derived by selective growth in a medium containing increasing concentrations of the BRAF inhibitor, vemurafenib." (PMID 37296851, 2023). "Melanoma phenotypic switching contributes to targeted BRAF treatment resistance." (PMID 37277330, 2023).
melanoma (continued). "Levels of OPN and MMP9 were correlated and higher in melanoma patients than in controls but, in those patients with the V600E BRAF mutation, the levels of both OPN and MMP9 were not different than in those patients without that mutation." (PMID 37444590, 2023). "In melanoma, BRAF mutant patients were treated with vemurafenib and PLX4720." (PMID 36830998, 2023). "An interesting hypothesis to explain such heterogeneity is that drug effectiveness may depend on a different metabolic vulnerability, reported as the Achilles’ heel of BRAF-driven melanoma." (PMID 37198319, 2023). "Our results may provide insights to further individualize and improve precision therapeutic decision-making in BRAF V600E-mutant and WT melanoma." (PMID 36704723, 2023). "Herein, we established a prognostic model based on the BRAF mutant of melanoma patients." (PMID 37205993, 2023). "Some previous Canadian studies have reported on BRAF status among melanoma patients." (PMID 37185430, 2023). "Recent clinical trials with ICI have shown remarkable improvements in long‐term patient outcomes with a 6.5‐year OS rate of 52% for BRAF‐mutant melanoma; however, treatment was accompanied by high rates of toxicities, whereby grade 3 or 4 toxicities were observed in 53% of patients." (PMID 36967556, 2023). "The recognition of the role of PAK1 in many BRAF wild-type cutaneous melanomas has brought about the question of whether it plays a similar role in the GNA-driven uveal form of the disease." (PMID 37830586, 2023). "Therefore, to better understand the connection between TERT expression and resistance to BRAF and MEK inhibitors, we conducted studies in BRAF-mutated melanoma cells." (PMID 37296851, 2023). "Another study that provides insights into the potential impact of MITF mutations on treatment response in the context of BRAF and NRAS mutations found that melanomas with concurrent NRAS and MITF mutations had distinct gene expression patterns and exhibited resistance to MAPK pathway inhibition." (PMID 37504268, 2023). "Numerous studies indicated that BRAF(V600E) mutant melanoma is one of the most glycolytic cancers." (PMID 38092752, 2023). "Molecular testing for activating BRAF variants has become standard of care as recommended by NCCN and the European Society for Medical Oncology (ESMO) for stage III or IV melanoma, to evaluate the eligibility and efficacy of BRAF/MEK inhibitors targeting the BRAF-MEK-ERK pathway." (PMID 37483495, 2023). "We provide evidence that BRAF inhibitor alone can be highly beneficial in BRAF mutant low-grade ovarian tumors and the resistance mechanisms are similar to that of other BRAF mutant tumors, including in melanoma." (PMID 36967525, 2023). "However, in another study, the nodular melanoma subtype did not prove to be an independent prognostic factor in advanced melanoma patients treated with BRAF- ± MEK-inhibitors or immunotherapy." (PMID 37664072, 2023). "Melanoma cells resistant to BRAF inhibitors have been shown to display increased oxphos." (PMID 37779896, 2023). "We report on 2 patients with BRAF V600E mutant melanoma, who presented with IR-sclerosing cholangitis under triplet therapy with atezolizumab [anti–programmed cell death ligand 1 (PD-L1) antibody], vemurafenib (BRAF inhibitor), and cobimetinib (MEK inhibitor)." (PMID 37728439, 2023). "Because the targeting of GREB1 Is4 could inhibit melanocytic melanoma growth in a different way from BRAF or immune checkpoint inhibitors, it paves the way for new clinical trials to eradicate malignant melanoma." (PMID 37658191, 2023).
melanoma (continued). "This multi‐center real‐world data study including 336 Asian patients with advanced BRAF V600‐mutant melanoma showed that the superiority of Anti‐PD‐1/CTLA‐4 over BRAF/MEK inhibitor appears modest, and the BRAF/MEK inhibitor remains a feasible first‐line treatment option." (PMID 37584204, 2023). "Regarding pERK1/2 and pAKT, which are both constitutively active in the BRAF-mutated melanoma cell lines, no different expression levels were found at short times (not shown) and after 24 h treatment in A375 and SK-Mel-28 cells." (PMID 36674794, 2023). "Likewise, HI-511, which targets both AURKB and BRAF V600E, has shown promise as a therapy against drug-resistant melanomas in the future." (PMID 36979496, 2023). "Later, the downregulation of p-AKT, p-mTOR, and p-P70S6K were obtained in A375 and BRAF mutation-negative melanoma cell line C8161 after treatment with curcumin." (PMID 36829966, 2023). "Since PPARGC1A silencing is expected to alter metabolic demands through impeding mitochondrial biogenesis, we used a metabolism-focused compound library to seek differential sensitivity between parental (drug naïve) and chronic treated BRAF-inhibitor resistant K029A melanoma cells." (PMID 37277330, 2023). "We proposed a prognostic model and evaluated some factors as type of surgery prior to adjuvant treatment or drug used for adjuvant treatment (e.g., anti-PD1 vs. BRAF/MEKi for selected BRAF/+/ melanoma patients) which could influence adjuvant treatment results." (PMID 37686659, 2023). "Furthermore, the tumors of patients with BRAF-WT melanomas are characterized by aggressive cell biology and an unfavorable prognosis." (PMID 38067230, 2023). "Interestingly, in a study utilising melanoma cells from patients who relapsed following treatment with BRAF or MEK targeted inhibitors, treatment with the FAK inhibitor (FAKi) defactinib was able to resensitise cells to killing by MAPK pathway inhibition." (PMID 37181747, 2023). "However, activation of the compensatory PI3K/Akt signaling cascade also occurs; indeed, Akt activation has been implicated in rendering acquired resistance to vemurafenib in BRAF-mutant melanomas." (PMID 37189846, 2023). "Anti-BRAF therapies failed to reproduce the impressive results observed for melanoma patients, despite the prevalence of BRAF mutation in more than 10% of patients with mCRC." (PMID 37511490, 2023). "In the IMMUNED study, a phase II study of postoperative dual immunotherapy versus single anti‐PD1 and placebo in patients with stage IV melanoma, nivolumab (NIVO) + ipilimumab (IPI) adjuvant therapy was superior to NIVO in terms of RFS in patients with BRAF mutation subtypes." (PMID 37016119, 2023). "The upregulation of WNT5A in BRAF inhibitor resistant melanomas could feasibly result from MAPK pathway reactivation, which would support an association between WNT5A and BRAFV600E signalling activity." (PMID 36539575, 2023). "Among the BRAF mutations identified thus far, BRAFV600E is most common with frequencies ~50% in melanomas, ~40% of papillary thyroid carcinomas, ~10% of colorectal cancers, ~5% of lung adenocarcinomas while also being detected in a subset of brain and hematological malignancies." (PMID 37834284, 2023). "Data have recently been published from the TRICOTEL clinical trial, a phase II study with 2 cohorts patients diagnosed with melanoma and BM: one cohort without BRAF V600 mutated tumors, and another one with BRAF V600 mutated ones." (PMID 38022574, 2023). "All patients with BRAF‐mutant melanoma underwent TTs as first‐line therapy." (PMID 38083908, 2023). "The development of targeted therapies for non-BRAF p.Val600-mutant melanomas remains a challenge." (PMID 36901951, 2023). "Pre-clinical data by several groups have suggested that combining BRAF/MEK inhibitors with PI3K/mTOR inhibitors may overcome resistance in BRAF mutant melanomas." (PMID 36983983, 2023).